CDKN2A (cyclin dependent kinase inhibitor 2A)
Diseases named in the same sentence as CDKN2A in open-access papers (continued):
Sharing a sentence is not in itself a finding about the gene and the disease.
type 2 diabetes (continued). "Genetic polymorphisms in CDKAL1, CDKN2A/2B, KCNJ11, KCNQ1, and PEPD that we selected as potential effect modifiers were found to be associated with type 2 diabetes in the East Asian population." (PMID 32722593, 2020). "We confirmed associations of SNPs in KCNQ1, CDKN2A/CDKN2B, CENTD2 and SLC30A8 with type 2 diabetes in Han Chinese." (PMID 25587982, 2015). "We confirmed the associations of genetic variations in SLC30A8, CDKN2A/CDKN2B, KCNQ1, CENTD2 with type 2 diabetes." (PMID 25587982, 2015). "In summary, we have identified significant associations between variants in CDKN2A/B, CDKAL1 and TCF7L2 and type 2 diabetes in a Han Chinese population." (PMID 20161779, 2010). "We have identified significant association between variants in CDKN2A/B, CDKAL1 and TCF7L2, and type 2 diabetes in a Han Chinese cohort, indicating these genes as strong candidates conferring susceptibility to type 2 diabetes across different ethnicities." (PMID 20161779, 2010). "Our results support previous findings that these variants in CDKN2A/B and CDKAL1 individually contribute to the risk of type 2 diabetes in the Han Chinese population, but imply some ethnic differences between Europeans and Asians." (PMID 20161779, 2010). "Genome-wide association studies (GWAS) have linked common single nucleotide polymorphisms (SNPs) on chromosome 9p21 near the INK4/ARF (CDKN2A/B) tumor suppressor locus with risk of atherosclerotic diseases and type 2 diabetes mellitus." (PMID 19343170, 2009). "Similarly, transcripts of candidate genes for type 2 diabetes (Blk, C2cd4a, C2cd4b, Cdkn2a, Hnf1a, Mtnr1b, Pou5f1, Slc30a8) and type 1 diabetes (Cd69, Il2, IL27) were not expressed in the brain." (PMID 39920851, 2025). "Furthermore, in AS and type 2 diabetes, the mRNA levels of CDKN2A (p16Ink4a), CDKN2B (p15Ink4b), and CDKN2BAS are reduced." (PMID 39519014, 2024). "CDKN2A can impact the occurrence and development of Type 2 diabetes through multiple mechanisms." (PMID 38904034, 2024). "Several type 2 diabetes susceptibility genes are known to play a role in cancer development (e.g. TCF7L2, CDKN2A/B, AKT2, PPARG, PTEN and HNF1B) but the evidence is relatively scarce for shared genetic aetiology between type 2 diabetes predisposing alleles and the observationally associated cancers." (PMID 32705315, 2020). "We did not observe significant interactions by five single nucleotide polymorphisms (SNPs) related to type 2 diabetes (CDKAL1 rs7756992, CDKN2A/B rs10811661, KCNJ11 rs5215, KCNQ1 rs163184, and PEPD rs3786897) in the association between coffee and the risk of type 2 diabetes." (PMID 32722593, 2020). "Furthermore multiple GWAS studies have identified the CDKN2A locus, particularly the region encoding the long non-coding RNA ANRIL which negatively regulates p16INK4A, as a hotspot for cardiovascular disease, type 2 diabetes, and frailty." (PMID 28473239, 2017). "In addition, the current study also replicated the significant associations of two other genes (CDKN2A/CDKN2B and SLC30A8) with type 2 diabetes susceptibility, which was consistent with the observations from other studies in Han Chinese." (PMID 25587982, 2015). "A majority of genes associated with type 2 diabetes from this meta-analysis (ADCY5, CDKAL1, CDKN2A/B, HHEX, IGF2BP2, SLC30A8, TCF7L2 and KCNQ1) are involved in pancreatic beta cell function, while two are implicated in insulin sensitivity (PPARG) and adiposity (FTO)." (PMID 25145545, 2014). "Most of the genes associated with type 2 diabetes (TCF7L2, SLC30A8, HHEX, CDKAL1, CDKN2A/B and IGF2BP2) might be implicated in beta cell function." (PMID 20161779, 2010).
type 2 diabetes (continued). "We replicated previous findings of associations for three SNPs in this Chinese population (rs10811661 in CDKN2A/B, rs10946398 in CDKAL1, and rs7903146 in TCF7L2) suggesting that some of the variants associated with type 2 diabetes in Europeans are also associated with the disease in Asians." (PMID 20161779, 2010). "However, in 2007, several reproducible genome-wide association studies (GWASs) confirmed these well-established susceptibility genes and identified a number of new loci (SLC30A8, HHEX, CDKN2A/B, IGF2BP2, GCKR, FTO, and CDKAL1) at which common variants influence risk of type 2 diabetes in Europeans." (PMID 20161779, 2010). "The genome wide association studies have identified various susceptibility genes, including several type 2 diabetes mellitus (T2DM) such as PPARG, TCF7L2, FTO, CDKN2A/2B, and IRS1 etc. to be associated with the risk of T2DM, though their definite relation with GDM remains to be explored further." (PMID 28083030, 2016). "Recently, several genome-wide and candidate gene association studies have identified many novel genetic loci for type 2 diabetes (T2D); among these genes, CDKAL1, IGF2BP2, SLC30A8, CDKN2A/B, HHEX, FTO, TCF2, KCNQ1, and WFS1 are the most important." (PMID 20509872, 2010). "We did not detect statistically significant interactions between coffee consumption and five SNPs related to type 2 diabetes (CDKAL1 rs7756992, CDKN2A/B rs10811661, KCNJ11 rs5215, KCNQ1 rs163184, and PEPD rs3786897) in the association between coffee and the risk of type 2 diabetes." (PMID 32722593, 2020). "Furthermore, a two-factor gene-environment interaction model of CDKN2A/B (rs10757274) and type 2 diabetes mellitus (T2DM) was identified to be the best model by GMDR (p = 0.0107), with a maximum prediction accuracy of 59.18%, and a maximum Cross-validation Consistency of 10/10." (PMID 25430018, 2014). "However, only the maturity-onset diabetes of the young (MODY) gene HNF4A and the T2D gene CDKN2A in SAT had significant permutation adjusted P-values." (PMID 23251491, 2012).
hepatocellular carcinoma (70 papers, 2002 to 2025). A malignant tumor that arises from hepatocytes. "In hepatocellular carcinoma, CDKN2A expression is associated with tumor purity and macrophage expression." (PMID 38888512, 2024). "We found that NEAT1 was upregulated in tumor tissues and hepatoma cells, which negatively correlated with a senescence biomarker CDKN2A encoding p16INK4a and p14ARF proteins." (PMID 37752791, 2023). "Four cell cycle-related genes (CDK4, CHEK1, CCNB1, and CDKN2A) were used to establish a risk score to predict the overall survival (OS) of patients with hepatocellular carcinoma (LIHC) in TCGA training set using LASSO Cox regression analysis." (PMID 36403263, 2022). "Interestingly, FOXM1 has been identified in hepatocellular carcinoma as a target of Alternate Reading Frame of the INK4a/ARF locus (CDKN2A), which also encodes p16ink4a." (PMID 26279295, 2016). "Abnormal expression of CDKN2A has been reported in hepatocellular carcinoma (HCC) and is associated with the prognosis of patients and infiltration of immune cells." (PMID 35771229, 2022). "Consistently, recent works also highlighted the driving function of CDKN2A in immune infiltration of hepatocellular carcinoma and tumor‐immune microenvironment formation of urothelial carcinoma." (PMID 39844467, 2025). "A combined analysis of data from five different tumors in TCGA revealed that patients with low CDKN2A expression had a better prognosis, with hepatocellular carcinoma and lung squamous carcinoma reaching significant levels." (PMID 40703650, 2025). "Previous research showed that CA significantly decreased the expression of the Cdkn2a and Cdkn1a genes in human dermal fibroblasts and human hepatoma cells." (PMID 40822955, 2025). "For instance, the CBX4 rs2289728 (G>A) SNP has been linked to a decreased risk of hepatocellular carcinoma (HCC), potentially by reducing CBX4 expression and alleviating repression of tumor suppressor genes like cyclin-dependent kinase inhibitor 2A (CDKN2A)." (PMID 40740235, 2025). "Huang’s group showed that competitive inhibition of the interaction between CDK4 and CDKN2A by PRMT5 is essential for glucose-induced hepatocellular carcinoma cell proliferation." (PMID 39255317, 2024). "During senescence, NEAT1 translocated into cytosol and interacted with a motor protein KIF11, resulting in KIF11 protein degradation and subsequent increased expression of CDKN2A in cultured hepatoma cells." (PMID 37752791, 2023). "CDKN2A inhibition combined with transcatheter arterial embolization (TAE) treatment can facilitate cancer-cell necrosis in rats with hepatic carcinoma." (PMID 36160009, 2022). "Another study suggested that CDKN2A is not only a prognostic marker but is also involved in immune infiltration in hepatocellular carcinoma." (PMID 36312586, 2022). "Rh2 also suppresses proliferation of hepatocellular carcinoma (HCC) cells by targeting EZH2 to regulate CDKN2A-2B gene cluster transcription." (PMID 31780945, 2019). "Overall, the CDK4 and CDKN2A (p16INK4a as the major isoform) complex is more critical for growth suppression in hepatoma cells or other types of tumor cells." (PMID 27708221, 2016). "Herein, we evaluated CDKN2A promoter methylation and p16 protein expression for the differentiation of hepatocellular carcinoma (HCC) from other liver tumors." (PMID 20569442, 2010). "The CDKN2A gene is often dysregulated in hepatocellular carcinomas by promoter methylation." (PMID 35453756, 2022). "In addition, it has been shown that CDKN2A is a new marker of poor prognosis in patients with hepatocellular carcinoma, which is consistent with our study." (PMID 36195876, 2022).
hepatocellular carcinoma (continued). "The up-regulation of cdkn2a expression in hepatocellular carcinoma may be related to the involvement of cdkn2a in the MAPK signaling pathway and the diversity of hepatocellular carcinoma." (PMID 35689249, 2022). "Furthermore, cox proportional-hazards model was used to validate the potential for CDKN2A as a prognostic factor of hepatocellular carcinoma clinical tissue samples." (PMID 34405225, 2021). "In summary, CDKN2A was an independent prognostic factor of patients with hepatocellular carcinoma." (PMID 34405225, 2021). "Nevertheless, the expression of CDKN2A was increased in hepatocellular carcinoma (HCC) and exhibited a significant correlation with unfavorable patient prognosis." (PMID 39408933, 2024). "(A) Genome browser tracks for MLL3 and H3K4me1 chromatin immunoprecipitation-sequencing (ChIP-Seq) in Myc; sgTrp53 (red) and Myc; sgKmt2c (blue) hepatocellular carcinoma (HCC) cell lines at the Cdkn2a locus." (PMID 37261974, 2023). "Mechanistically, the CDKN2A locus is a genomic and transcriptional target of KMT2C in hepatocellular carcinoma cells, and KMT2C mediates oncogene-induced apoptosis in a CDKN2A-dependent manner." (PMID 39165358, 2024). "We also used a GSE84402 dataset to validate the mRNA expression levels of IGF1, CDKN2A, BIRC5, and SPP1 in hepatocellular carcinoma tissues and adjacent tissues." (PMID 39042294, 2024). "CDKN2A expression was positively correlated with infiltrating levels into CD8+ T cells, CD4+ T cells, and neutrophils in hepatocellular carcinoma." (PMID 35937995, 2022). "Cyclin dependent kinase inhibitor 2A (CDKN2A) is an essential regulator of immune cell functionality, but the mechanisms whereby it drives immune infiltration in hepatocellular carcinoma (HCC) remain unclear." (PMID 34405225, 2021). "In a study of lncRNA-NEAT1 and HCC cell senescence, lncRNA-NEAT1 is highly expressed in tumor tissues and hepatocellular carcinoma cells, while the expression of CDKN2A, a biomarker of aging encoding p16INK4a and p14ARF proteins, is decreased, demonstrating a negative correlation." (PMID 40110044, 2025).
diabetes (68 papers, 2009 to 2025). "Diabetes increased kidney expression of genes associated with injury (Kim1, ten-fold), senescence (Cdkn1a, Cdkn2a, 10 to 18-fold) and fibrosis (Tgfb1, Ctgf, Pai1, Timp1, Col1α1, Col4α1 and Fn1, two- to six-fold)." (PMID 41332229, 2025). "The CDKN2A/B locus, the cyclin-dependent kinase inhibitor 2 A/B gene at chromosome 9p21, influences diabetes risk through islet gene expression, β-cell proliferation, and non-islet mechanisms." (PMID 35740093, 2022). "Genome-wide association studies (GWASs) have unequivocally linked the CDKN2A locus with human diabetes risk, although the mechanisms remain uncertain." (PMID 34439790, 2021). "In line withprevious studies, our data associates CDKN2A/B withthe risk of diabetes in the offspring of mothers withgestational diabetes." (PMID 31721535, 2020). "Nonetheless, the procedure, throughwhich the CDKN2A/B locus affects diabetes risk is yet tobe discovered." (PMID 31721535, 2020). "CDKN2A/B, the cyclin-dependent kinase inhibitor 2 A/B gene, impacts diabetes risk across various ethnicities and geographical locations via β-cell mass and proliferation." (PMID 29777116, 2018). "Only a single genetic variant (CDKN2A/B rs564398) associated significantly with CHD after adjustment for diabetes." (PMID 23185617, 2012). "A nominally significant genotype–treatment interaction effect on diabetes incidence had been reported for the CDKN2A/B rs10811661 variant; however, treatment-stratified genotype–diabetes associations were not significant in any of the placebo, lifestyle, or metformin groups." (PMID 24845081, 2014). "Although the gene products at CDKN2A/B play roles in many cell types, strong evidence links CDKN2A/B T2D risk-polymorphisms specifically to impaired insulin secretory function in humans, pointing to impact on pancreatic islets as the causative mechanism by which this gene locus drives diabetes risk." (PMID 35546161, 2022). "However, the mechanism by which the CDKN2A/2B locus influences diabetes risk remains uncertain." (PMID 29871606, 2018). "To further validate the protein expression levels of the five key diabetes-related genes (CDKN2A, GSN, PGR, SELENOP, and TRPC1) identified in our prognostic model, we utilized IHC staining data from the HPA database." (PMID 41244925, 2025). "In our model, we identified five differentially expressed diabetes-related genes, with GSN and PGR exhibiting heightened expression levels in the low-risk group, whereas CDKN2A, SELENOP, and TRPC1 demonstrated increased expression in the high-risk group." (PMID 41244925, 2025). "For example, lncRNA ANRIL, located in the p15/CDKN2B-p16/CDKN2A-p14/ARF, has been shown through genome-wide association studies to be genetically associated with diverse diseases such as diabetes, cancer, and heart disease." (PMID 38027148, 2023). "In murine models, overexpression of Cdkn2a leads to decreased islet proliferation in aging mice and that of Cdkn2b leads to islet hypoplasia and diabetes." (PMID 33017871, 2020). "We have also checked the differences in these markers according to the duration of diabetes, which indicated that MCP-1 (p = 0.002) and CDKN2A (p < 0.001) significantly increased with the duration of diabetes." (PMID 32280716, 2020). "We also found association between CDKN2A/2B (rs10811661), SLC30A8 (rs13266634), and TCF7L2 (rs7903146) and diabetes-related quantitative traits." (PMID 29871606, 2018). "Since the expression of these genes is lost in immortalized and transformed cell lines, such systems would be ineffective to determine the role of genes such as CDKN2A in diabetes, as well as any gene that interacts with this role." (PMID 23840313, 2013). "Therefore, further research is needed to uncover the involvement of CDKN2A in cuproptosis and explore potential connections between CDKN2A and the regulation of both cuproptosis and diabetes." (PMID 38904034, 2024). "In summary, CDKN2A, a crucial gene regulating the cell cycle, holds significance in diabetes." (PMID 38904034, 2024).